BRAF (B-Raf proto-oncogene, serine/threonine kinase)
Diseases named in the same sentence as BRAF in open-access papers (continued):
Sharing a sentence is not in itself a finding about the gene and the disease.
papillary thyroid carcinoma (continued). "Thus, combined therapy using HER inhibitor and BRAF/MEK inhibitor presented more significant redifferentiation effect on papillary thyroid cancer cells harboring BRAFV600E than BRAF/MEK inhibitor alone." (PMID 28423638, 2017). "For example, BANCR (BRAF-activated lncRNA) could increase cell proliferation in papillary thyroid cancer (PTC, PTC accounts for approximately 80% of all THCA in adults), and its levels were significantly higher in PTC." (PMID 29340074, 2017). "The mutual exclusivity of the NRAS, HRAS, and BRAF mutations in THCA tumors has been interpreted to mean that these mutations must have interchangeable effects on MAPK signaling activation, the main cancer-driving event in papillary thyroid carcinomas." (PMID 29125844, 2017). "In papillary thyroid cancer, KLK7 upregulation was found to be correlated with BRAF mutations." (PMID 28636767, 2017). "The combination of lenvatinib with other targeted agents, such as mTOR inhibitors, is a promising area of investigation, while MEK inhibitors, BRAF inhibitors and immune-oncology agents also show promise for treating radioiodine-refractory, differentiated thyroid cancer." (PMID 31093354, 2017). "We identified 14 hits whose silencing was able to significantly reduce the viability and the proliferation of TPC1 cells; most of them were active also in BRAF-mutant BCPAP (papillary thyroid cancer) and 8505C (anaplastic thyroid cancer) and in RAS-mutant CAL62 (anaplastic thyroid cancer) cells." (PMID 27058903, 2016). "Not all studies have consistently shown this mutation to be associated with higher risk for a more aggressive clinical course, nor is the clinical ramification of the BRAF mutation identical in all subtypes of papillary thyroid cancer." (PMID 26886959, 2016). "As it has been noted on previous work: CST6, CXCL14, DHRS3, and SPP1 are regulated by BRAF signaling and may play a role in papillary thyroid carcinoma pathogenesis." (PMID 25887408, 2015). "BRAF mutation was not identified in any of the follicular adenomas and corresponding normal parts of papillary thyroid cancer." (PMID 24559116, 2014). "Moreover, BRAF testing confirmed 82.4% of papillary carcinomas with suspicious cytology and identified 33.3% of papillary carcinomas with atypia cytology." (PMID 24591770, 2014). "Although the number of analyzed samples was not large, preferentially methylated papillary thyroid cancer showed mutation of BRAF/RAS oncogenes more frequently than methylation(−) cancer (P = 0.04, Fisher's exact test)." (PMID 24367375, 2013). "For papillary thyroid cancer, matching was done with a 1∶1 ratio due to an inadequate number of patients referred who had tests done and tested negative for BRAF mutation." (PMID 22039425, 2011). "BRAF V600E as a target may not be limited to only PTC with a BRAF activating mutation, since BRAF and other RAF kinases are activated by other oncogenes involved in follicular and papillary carcinoma." (PMID 22654559, 2011). "A number of gene alterations, such as point mutations in RAS and BRAF genes, point mutations or amplification of PIK3CA, and fusion genes involving RET, NTRK1 and PPARγ are known to frequently occur in differentiated thyroid carcinoma, and are correlated to different morphological subtypes." (PMID 22087789, 2011). "In papillary thyroid cancer (PTC), BRAF mutation (and hence activation of the MAPK pathway) was associated with decreased radioiodine avidity, which can be explained by BRAF mutation-associated silencing of thyroid iodide-handling genes, such as NIS, Tg, and TPO." (PMID 19593429, 2009). "RET proto-oncogene rearrangements (frequency: ∼30% in adult PTC) and BRAF somatic mutations (frequency: 36–69% in adult PTC) represent the most common genetic alterations found in sporadic, naturally occurring, papillary thyroid carcinomas (PTC)." (PMID 15812549, 2005).
papillary thyroid carcinoma (continued). "Conversely, BRAF V600E mutations, while prevalent in classic papillary thyroid carcinoma (PTC), are rare or absent in NIFTP but may occur in FVPTC, particularly in infiltrative or aggressive subtypes." (PMID 41194828, 2025). "Besides, the incorporation of molecular markers, such as BRAF, RAS and TERT detection, enhances the diagnostic value of thyroid nodules exhibiting indeterminate cytology, and plays a role in predicting outcomes for patients with papillary thyroid carcinoma." (PMID 40510463, 2025). "While BRAF V600E was selected as a proof-of-concept marker because of its established role in papillary thyroid carcinoma, the broader implication lies in showing that CytoMatrix may serve as a platform for routine molecular testing within standard cytopathology practice." (PMID 41303583, 2025). "The aim of this study was to investigate the relationship between the presence of the BRAF, HRAS, NRAS, and KRAS gene mutations and the development of dedifferentiation (iodine-refractory disease) and extrathyroidal disease in patients with differentiated thyroid carcinoma (DTC)." (PMID 40104288, 2025). "In many previous investigations, 87% of instances of squamous cell carcinoma of the thyroid, whether it contained differentiated thyroid cancer or not, had BRAF V600E mutations, and its prognosis was comparable to that of anaplastic thyroid carcinoma." (PMID 38737660, 2024). "The results showed that the downregulation of KIF-12 expression enhances the progression of differentiated thyroid carcinoma, and the effect may be more significant among younger female patients with unifocal PTC showing lymph node metastasis and BRAF mutation." (PMID 38495495, 2024). "Additionally, although BRAF mutation has a negative prognostic role in papillary thyroid carcinoma, the overall favorable prognosis of this malignancy limits the impact of BRAF on long-term patient outcomes." (PMID 36077604, 2022). "Moreover, OPN can be related to EMT-associated RAS/MAPK activation through the expression of BRAF; in papillary thyroid cancer, high OPN expression was associated with the BRAF V599E mutation along with advanced tumors and lymph node metastasis, and also with BRAF V600E mutated tumors." (PMID 34680488, 2021). "Molecular re-examination of the primary follicular variant papillary thyroid carcinoma demonstrated a codon 600 BRAF mutation and a TERT promoter wildtype sequence, while the primary TCV-PTC was positive for mutations in both codon 600 of BRAF as well as the TERT promoter." (PMID 33466206, 2021). "This transversion causes a conversion of valine to glutamate of amino acid 600 in the BRAF protein, creating a constitutively active BRAF kinase, which has been proven to be an oncogene in human cancer and is found in 40%–80% of all cases of papillary thyroid cancer." (PMID 29316976, 2018). "In contrast, in 27 sporadic papillary thyroid cancers that occurred in non-contaminated children from Ukraine, gene rearrangements were found in 9, and BRAF (n = 7) or NRAS (n = 2) gene point mutations were found in 9 tumors, and no driver mutation was found in 9 tumors." (PMID 28225863, 2017). "BRAF V600E was found in 70% of the papillary thyroid cancers; there were no RAS mutations." (PMID 25019383, 2014). "Together with the recent finding of BRAF mutations in papillary thyroid carcinomas activation of RAS or downstream signalling might not be a strong requisite for tumor progression and malignant transformation of follicular thyroid lesion." (PMID 22654559, 2011).
papillary thyroid carcinoma (continued). "In cases, RET/PTC rearrangements are found in 30%–40%, RAS mutations in about 10%, and BRAF mutations in around 40%–50%, with no overlap between these mutations results in papillary thyroid cancer, while a higher prevalence of BRAF mutations (up to 70%) has been observed in DeTC." (PMID 20628483, 2010). "It will be a direct proof of fetal cell carcinogenesis hypothesis when a BRAF mutation is observed only in coexisting papillary carcinoma but not in anaplastic carcinoma." (PMID 17453004, 2007). "However, BRAF expression is less common in FVPTC as compared to classic papillary carcinoma; therefore, its use in the diagnosis of FVPTC in FNA specimens may be of limited value." (PMID 16603062, 2006). "In the second study of nine healthcare workers with papillary thyroid carcinoma (PTC) exposed to LDIR, BRAF V600 genetic alterations were revealed in four cases, including one with RET/PTC1 fusion, and in one case, point mutations and fusions were found." (PMID 39860597, 2025). "Multi-gene joint analysis of RET C634R in the left nodule and BRAF V600E in the right nodule indicated a potential diagnosis of left medullary thyroid carcinoma (MTC) and right papillary thyroid carcinoma (PTC)." (PMID 40017634, 2024). "In a study that included 14 patients with differentiated thyroid cancer (DTC), the most common genetic alteration was in the NRAS codon 61, whereas BRAF V600E was less frequent." (PMID 37374352, 2023). "And schematic of mechanism of BRAF-activated WT1 contributes to cancer growth and regulates autophagy and apoptosis in papillary thyroid carcinoma." (PMID 35123502, 2022). "On the other end, BRAF V600E and similar molecular alterations such as RET and NTRK rearrangement are the defining molecular markers for “conventional” papillary thyroid carcinoma, i.e., those characterized by the presence of neoplastic papillae." (PMID 33543394, 2021). "Endocannabinoids were effective against cancer cells with activated BRAF/ERK and/or TrkA signaling, suggesting their potential utility for the treatment of BRAF-positive papillary thyroid carcinoma (PTC) and TrkA-positive medullary thyroid cancer." (PMID 31979368, 2020). "Radical total thyroidectomy was done in January 2015 and verified multifocal papillary carcinoma (mixed follicular variant and focal insular/solid variant) 8.4 × 4.3 × 4.0 cm in size with lymphovascular invasion and extrathyroid extension to the muscle, negative for BRAF V600E gene mutation." (PMID 31103041, 2019). "Detection of BRAF and RET/PTC rearrangements is widely used in clinical diagnosis of papillary thyroid carcinoma." (PMID 29449788, 2018). "The aim of this study was to determine BRAF, RAS (K-RAS, H-RAS, N-RAS), and RET/PTC (RET/PTC1, RET/PTC3) gene alterations in thyroid papillary carcinoma and evaluate the utilization of molecular testing in the diagnosis of FNA in a Chinese population." (PMID 24591770, 2014). "Our laboratory evaluated cellular phenotypic effects in response to treatment with PLX4032, a BRAFV600E-specific inhibitor, in normal BRAF-wild-type thyroid cells and in BRAFV600E-positive papillary thyroid cancer cells." (PMID 24673746, 2014). "In Middle Eastern papillary thyroid carcinoma, synergistic effect of PIK3 and BRAF suggest their role in tumorogensis." (PMID 23768168, 2013). "BRAF mutations and RET/PTC rearrangements are mutually exclusive in papillary carcinomas, both activating constitutively the RET/PTC–RAS–BRAF–MAPK pathway." (PMID 15812549, 2005). "Unlike high specificity (up to 98%) of BRAF V600E in papillary thyroid carcinoma, no effective genetic markers have been identified to differentiate FTC and FTA, not even a panel of gene markers." (PMID 40442320, 2025).
papillary thyroid carcinoma (continued). "Oncogenic fusions involving tensins include TNS1::BRAF in BRAF-negative papillary thyroid carcinomas (identified in a cohort of 62 cases) and FGFR2::TNS1 detected in circulating tumor DNA from biliary tract cancer patients (102 cases)." (PMID 40906372, 2025). "Notably, substantial correlations have been identified between BRAF V600E and TERT promoter genetic changes, with especially frequent simultaneous presence detected in papillary thyroid carcinomas and skin melanomas." (PMID 40469184, 2025). "Differentiated thyroid cancers such as follicular thyroid carcinoma (FTC) and papillary thyroid carcinoma (PTC) have specific genetic alterations that correlate with morphological classifications: RAS-like tumors (RLTs) and BRAF p.V600E-like tumors (BLTs), respectively." (PMID 38672067, 2024). "In summary, we presented a case of a 48-year-old man with a concurrent diagnosis of papillary thyroid cancer and LCH with non-concordant BRAF mutation status." (PMID 38657650, 2024). "We analyzed the TCGA papillary thyroid cancer dataset and found that RET-rearranged cancers have higher levels of ERK activity compared with BRAF/RAS mutant cancers, which may be the basis for a sensitivity to adaptive resistance after RET inhibition." (PMID 35510953, 2022). "We compared the ERK score, a measure of ERK activity derived from RNAseq data, from RET-rearranged, BRAF mutant, and RAS mutant papillary thyroid cancers in TCGA patients, and we found that RET-rearranged cancers have significantly higher ERK scores than either BRAF or NRAS/HRAS mutant tumors." (PMID 35510953, 2022). "We also observed that 45.7% of BRAF negative thyroid carcinoma samples had EGFR mutation, with 71.4% was found in papillary thyroid carcinoma." (PMID 36510281, 2022). "Overall, 101 BRAF V600E mutations were detected by ddPCR, including five ARMS negative patients, four of whom were confirmed to have papillary thyroid cancer (PTC) by surgical pathology." (PMID 32671901, 2020). "No mutations of BRAF and NRAS were found in 28 cases (53%; 16 patients with papillary thyroid cancer, 8 patients with follicular variant; 3 patients with follicular thyroid cancer, 1 patient with oxyphilic variant)." (PMID 28493027, 2017). "In Chinese patients with papillary carcinoma, TERT promoter mutations rather than BRAF V600E mutations were associated with a more advanced TNM stage and shorter progression-free survival." (PMID 29108240, 2017). "Relative expression of six microRNAs (miR-146b, −21, −221, −222, 375, −199b) appeared significantly different in BRAF(V600E)-positive samples (all classified as papillary thyroid carcinomas) compared to BRAF(V600E)-negative papillary carcinoma samples." (PMID 26960768, 2016). "It detected V600E mutation in 22 out of 33 (67%) of the conventional papillary thyroid carcinoma (PTC), 8 out of 12 (75%) of the tall-cell variant of PTC, whereas none of the 10 follicular variant of PTC showed BRAF V600E mutation." (PMID 24252159, 2013). "Ex vivo BRAF V600E-specific dabrafenib kinase inhibition identified 6/92 analyzed peptides, capable of differentiating BRAF V600E-mutant from non-BRAF V600E papillary thyroid cancers (PTCs), an effect not seen with the generic inhibitors sorafenib and regorafenib." (PMID 37760447, 2023). "Mutations of the v-Raf murine sarcoma viral oncogene homolog B (BRAF) oncogene and telomerase reverse transcriptase (TERT) promoter region are indicators of poor prognosis in papillary thyroid carcinoma (PTC) and might predict future occurrences of distant metastases." (PMID 33466206, 2021). "For instance, the PKI sorafenib inhibits the kinases RAF, BRAF, FLT3, VEGFR 1–3, PDGFR, c-KIT and RET and significantly improves progression-free survival compared with placebo in patients with progressive radioactive iodine-refractory differentiated thyroid cancer." (PMID 34888523, 2021).
papillary thyroid carcinoma (continued). "Moreover, considering the fact that RAS proto-oncogene mutation is only reported in 20% of patients with papillary carcinoma, studying the simultaneous occurrence of RAS and BRAF mutation is not of much importance." (PMID 23815863, 2013). "Additionally, in a study of BRAF mutated Papillary Thyroid Carcinoma (PTC), c-Met expression was 3-fold higher in the BRAF aggressive PTC vs. the BRAF non-aggressive PTC." (PMID 22745804, 2012). "Similarly, various fusions of BRAF have been implicated in cancer such as pediatric astrocytomas (KIAA1549-BRAF; exons 9/11), melanocytic nevi (FCHSD1-BRAF; exon 9), papillary thyroid carcinomas (AKAP9-BRAF; exon 9), prostate cancer (SLC45A-BRAF; exon 8), and gastric cancer (AGTRAP-BRAF; exon 8)." (PMID 22745804, 2012). "Additionally, we could not detect the typical common driver mutations of differentiated thyroid carcinoma genes related to the MAP-Kinase signaling pathway, including BRAF and RAS." (PMID 32124226, 2020). "The objective of these experiements was to increase the pre-operative FNA diagnostic sensibility, as the BRAF mutation does not occur together with the RAS mutation or the RET-PTC rearrangement, indicating different genetic alterations in the pathogenesis of the papillary carcinoma." (PMID 23946802, 2013). "As controls, we used DNA isolated from FFPE sections of a papillary thyroid carcinoma (PTC) and a follicular thyroid adenoma (FTA) known as positive and negative for BRAF V600E, respectively." (PMID 34135377, 2021).